RNU6-917P (RNA, U6 small nuclear 917, pseudogene)
Gene: Small nuclear RNA gene on chromosome 20 (1,529,056 to 1,529,159, reverse strand). Ensembl gene ENSG00000252103.
Homologues: Orthologues: chimpanzee U6 (98% identical), macaque U6 (98% identical), mouse Gm24538 (82% identical), dog U6 (76% identical), guinea pig U6 (62% identical), mouse Gm22157 (59% identical). Paralogues in human: RNU6-1152P (84% identical), RNU6-19P (84% identical), RNU6-211P (84% identical), RNU6-961P (84% identical), RNU6-166P (83% identical), RNU6-203P (83% identical), RNU6-41P (83% identical), RNU6-509P (83% identical), RNU6-562P (83% identical), RNU6-820P (83% identical), RNU6-1010P (82% identical), RNU6-1060P (82% identical), and 1286 more.